COL4A6 (collagen type IV alpha 6 chain)
Description:
Type IV collagen is the major structural component of glomerular basement membranes (GBM), forming a 'chicken-wire' meshwork together with laminins, proteoglycans and entactin/nidogen.
Synonyms: CXDELq22.3; DELXq22.3; DFNX6
Tractability: Antibody: its Gene Ontology location is reachable by antibodies, with high confidence; UniProt places it where antibodies can reach, with medium confidence; UniProt predicts a signal peptide or a membrane-spanning region. PROTAC: ubiquitination databases record sites on it. Other modalities: an approved drug acts on it.
Gene: Protein-coding gene on chromosome X (108,155,607 to 108,439,497, reverse strand). Ensembl gene ENSG00000197565.
Subcellular location: Secreted, extracellular space, extracellular matrix, basement membrane
Subcellular location (Human Protein Atlas): Endoplasmic reticulum; Predicted to be secreted
Pathways (Reactome):
Extracellular matrix organization: Anchoring fibril formation; Assembly of collagen fibrils and other multimeric structures; Collagen biosynthesis and modifying enzymes; Collagen chain trimerization; Collagen degradation; Crosslinking of collagen fibrils; ECM proteoglycans; Fibronectin matrix formation; Integrin cell surface interactions; Laminin interactions; Non-integrin membrane-ECM interactions
Cellular responses to stimuli: Attenuation phase; HSF1 activation; HSF1-dependent transactivation; Regulation of HSF1-mediated heat shock response
Disease: Attachment of bacteria to epithelial cells
Gene Ontology:
Molecular function: extracellular matrix structural constituent conferring tensile strength; protein binding; extracellular matrix structural constituent
Biological process: collagen fibril organization; collagen-activated tyrosine kinase receptor signaling pathway; extracellular matrix organization
Cellular component: basement membrane; extracellular matrix; collagen type IV trimer; endoplasmic reticulum lumen; extracellular region; collagen trimer
Gene-disease validity (ClinGen):
ClinGen rates the evidence that COL4A6 causes each of these diseases.
hearing loss, X-linked 6 (X-linked): Limited.
Homologues: Orthologues: chimpanzee COL4A6 (99% identical), macaque COL4A6 (97% identical), dog COL4A6 (84% identical), rabbit COL4A6 (83% identical), mouse Col4a6 (80% identical), guinea pig COL4A6 (80% identical), rat Col4a6 (79% identical), pig COL4A6 (76% identical), Caenorhabditis elegans emb-9 (45% identical), Drosophila melanogaster vkg (40% identical). Paralogues in human: COL4A2 (52% identical), COL4A4 (50% identical), COL4A5 (49% identical), COL4A1 (48% identical), COL4A3 (45% identical), COL7A1 (35% identical), COL5A1 (33% identical), COL11A1 (32% identical), COL11A2 (32% identical), COL5A3 (31% identical), COL2A1 (30% identical), COL5A2 (29% identical), and 25 more.
Diseases named in the same sentence as COL4A6 in open-access papers:
COL4A6 is named in the same sentence as 60 diseases in open-access papers, as found by Europe PMC text mining. Sharing a sentence is not in itself a finding about the gene and the disease. The quoted sentences say what the papers report.
prostate carcinoma (12 papers, 2017 to 2025). A carcinoma that arises from epithelial cells of the prostate gland. "The downregulation of COL4A6 was associated with prostate cancer progression and metastasis, and the overexpression of GADL1 was associated with cancer cell migration and morphology (including cell area, thickness, volume, perimeter length, irregularity, and eccentricity)." (PMID 34445498, 2021). "The diminished expression of COL4A4 is associated with poorer prognosis, while the downregulation of COL4A6 promotes prostate cancer progression and invasion." (PMID 38907304, 2024). "COL4A6 is highly downregulated in prostate cancer, and its deletion can promote prostate cancer progression and metastasis by activating the p-focal adhesion kinase (FAK)/matrix metallopeptidase 9 (MMP-9) signaling pathway." (PMID 36353536, 2022). "Downregulation of COL4A5 and COL4A6 was correlated with metastasis in different cancers including melanomas, colorectal cancer, follicular thyroid cancer, prostate cancer, basal cell carcinoma, and breast cancer 48-53." (PMID 34104083, 2021). "Our observations are consistent with reports of COL4A6 downregulation in a range of cancers, including prostate cancer." (PMID 28052017, 2017). "The genes ITGBL1, DSC3, COL4A6, ANGPT1, ARMCX1, MICAL2, and EPHA5 have been recognized as pivotal genes that substantially affect the microenvironment of prostate cancer." (PMID 40943497, 2025). "We found that hypermethylation of COL4A6, CYBA, LINC01341, and RHCG was highly prostate cancer-specific, suggesting particularly promising diagnostic potential for these genes." (PMID 28052017, 2017). "COL4A6 (collagen type IV alpha six chain) is involved in cancer progression and invasion, whose expression correlates positively with the DFS of patients in prostate cancer." (PMID 33644115, 2021).
Alport syndrome (10 papers, 2015 to 2025). A rare renal disease characterized by glomerular nephropathy with hematuria progressing to end-stage renal disease (ESRD), frequently associated with sensorineural deafness, and occasionally with ocular anomalies. "The only candidate disease variant we observed was a non-synonymous alteration in the Collagen Type IV Alpha 6 Chain (COL4A6) gene that is involved in X-linked non-syndromic sensorineural deafness, Alport syndrome and leiomyomatosis." (PMID 31694657, 2019). "Examples include large deletions encompassing TSC2 and PKD1, resulting in a combined phenotype of tuberous sclerosis complex and autosomal dominant polycystic kidney disease, as well as deletions involving COL4A5 and COL4A6, which cause Alport syndrome with diffuse leiomyomatosis." (PMID 41303235, 2025). "Critically, the COL4A6 gene has been pointed out to be a candidate gene for Alport Syndrome by co-deletion in addition to the COL4A5 gene." (PMID 40718208, 2025). "Alport syndrome-diffuse leiomyomatosis is a rare type of X-linked Alport syndrome resulting from contiguous deletions of 5′ exons of COL4A5 and COL4A6." (PMID 34778325, 2021). "Mutations in the COL4A5 and COL4A6 genes which compromise the production of α5(IV)α5(IV)α6(IV) heterotrimers, result in thinning of the ILM and nerve fiber layer in Alport’s syndrome." (PMID 26230410, 2015). "As in the case of Alport syndrome associated with the contiguous deletion of the COL4A5 and COL4A6 genes, excluding the association of the COL4A6 gene with said syn-drome, it would be interesting to identify the clinical or molecular relevance of the inactivation of the CLCNKA gene alone in BS." (PMID 34768847, 2021). "Mutations in COL4A6 alone have not been related to Alport syndrome, but a COL4A6 mutation is linked to hereditary hearing loss, which is a more restricted symptom compared to Alport syndrome, implying that the Col4a5/Col4a6 complex has a more limited role in BM integrity in humans than in zebrafish." (PMID 26451951, 2015). "The report mentioned that deletion of the 5′ exons of COL4A6 is not needed to develop diffuse leiomyomatosis in patients with Alport syndrome, contrary to the recognised gene deletion characteristics of patients with AS-DL." (PMID 34778325, 2021).
breast carcinoma (7 papers, 2011 to 2025). "Our results show that COL4A6 was significantly downregulated in patients with Basal-subtype breast cancer, and this low expression was associated with poor prognosis (RFS)." (PMID 33644115, 2021). "COL4A6 was also identified as a key gene associated with survival of cancer cells in breast cancer." (PMID 33644115, 2021). "We found that two linker genes COL4A6 (p = 0.01) and PLK1 (p = 0.07) whose expressions are weakly associated with the survival of breast cancer patients." (PMID 25137136, 2014). "COL4A6 downregulation correlates with metastasis in various cancers, including melanoma, colorectal cancer, follicular thyroid cancer, prostate cancer, basal cell carcinoma, and breast cancer." (PMID 40603853, 2025). "The down-regulated expression of COL4A6 has been certified in breast cancer." (PMID 25137136, 2014). "In the selected key specific DEGs for Basal-subtype breast cancer, the altered expression of SOX11, PLK1, BUB1, OGN, COL4A6, AGTR1, and ADRB2 were significantly correlated with the prognostic survival of the patients." (PMID 33644115, 2021). "SOX11, PLK1, BUB1, OGN, COL4A6, AGTR1, and ADRB2 may be involved in the recurrence of Basal-subtype breast cancer, and to some extent the PLK1, BUB1, OGN, COL4A6, AGTR1, and ADRB2 can be used as the specific prognostic markers for Basal-subtype breast cancer." (PMID 33644115, 2021). "In these terms, aside from the genes COL4A6, COL6A2 and COL14A1 belonging to the collagen family, Tenascin-X (TNXB), which was described as a metastasis signature in breast cancer, was also up-regulated in our experiment but has not previously been reported for gastric cancer." (PMID 21435268, 2011).
leiomyoma (7 papers, 2017 to 2025). A well-circumscribed benign smooth muscle neoplasm characterized by the presence of spindle cells with cigar-shaped nuclei, interlacing fascicles, and a whorled pattern. "COL4A5/COL4A6 mutated leiomyomas have also been shown to have significantly elevated prolactin and associated genes in genome-wide association studies (GWAS)." (PMID 38957794, 2024). "According to studies conducted by Mehine and colleagues, alterations in the COL4A5/COL4A6 locus arose in multiple uterine leiomyoma samples through chromothripsis, a series of complex chromosomal rearrangements associated with aggressive cancer types and tumors, such as leiomyomas." (PMID 38957794, 2024). "A hypothesis is that the partially deleted COL4A6 gene expresses a truncated α6 (IV) chain, which leads to leiomyoma." (PMID 34778325, 2021). "The mechanism of leiomyoma caused by COL4A6 deletion is not completely clear." (PMID 34778325, 2021).
hearing loss (5 papers, 2015 to 2021). "Various genes encoding ECM or ECM-related proteins reportedly cause hereditary hearing loss, including COL4A6, which encodes the sixth alpha chain of collagen IV." (PMID 33848312, 2021). "Patients with hearing loss caused by the X-linked hereditary mutation of COL4A6 were reported to have malformed cochlea, as determined using high-resolution CT." (PMID 33848312, 2021). "Recently, the missense mutation (c.1771G>A, p.Gly591Ser) in COL4A6, encoding the basement membrane (BM) collagen α6(IV) chain, was shown to be associated with X-linked congenital nonsyndromic hearing loss with cochlear malformation." (PMID 33848312, 2021). "However, the mechanism by which the COL4A6 mutation impacts hereditary hearing loss has not yet been elucidated." (PMID 33848312, 2021).
colorectal cancer (4 papers, 2021 to 2025). A primary or metastatic malignant neoplasm that affects the colon or rectum. "Moreover, the loss of expression of the COL4A5 and COL4A6 chains in colorectal cancer has been linked to the hypermethylation of their promoter regions." (PMID 39845732, 2025). "Previous research has reported the downregulation of COL4A5 and COL4A6 expression in colorectal cancer." (PMID 38907304, 2024).
deafness (4 papers, 2018 to 2025). An inherited or acquired condition characterized by the complete loss of the ability to hear from one or both ears. "These cells expressed several causal genes for various deafness forms, including Eps8l2, Gjb2, Gjb6, Homer2, Coch, Clic5, Dcdc2a, Pou3f4, Col4a6, and Six1." (PMID 37339214, 2023).
colon cancer (3 papers, 2013 to 2023). "COL4A6 encodes one of the six subunits of type IV collagen likely involved in cell to cell adhesion and was found to be mutated in ovary cancer and colon cancer." (PMID 23301059, 2013). "In vitro studies demonstrated that the expression of COL4A5/COL4A6 genes was down-regulated in colon cancer cell lines, suggesting that normal basement membranes were disrupted in progressive tumors, accompanied by a down-regulation of gene expression." (PMID 36674696, 2023). "In colon cancer, the level of collagen expression is the key indicator to predicting the OS and risk, especially the types of COL1A1, COL1A2, COL3A1, COL4A3, and COL4A6." (PMID 36142424, 2022). "In addition, 5 other mutated genes were previously reported in colon cancers including FAM181A, NRXN3, KIAA1409, TFR2, and COL4A6." (PMID 23301059, 2013).
gastric cancer (3 papers, 2011 to 2025). A primary or metastatic malignant neoplasm involving the stomach. "Mutations in the COL4A6 gene are linked to peritoneal carcinomatosis in gastric cancer." (PMID 40943497, 2025).
epithelial ovarian cancer (2 papers, 2023 to 2025). "We found that the loss of CTGF in epithelial ovarian cancer cells is associated with modifications on the expression of several genes associated with the ECM, including LAMC2 SPP1, SV2A, RELN, COL6A3, and COL4A6." (PMID 37835529, 2023). "This study aimed to investigate the role of collagen type IV alpha 6 (COL4A6) in cell invasiveness, tumor formation, chemoresistance, and the prognostic impact of COL4A6 expression in ovarian cancer." (PMID 40603853, 2025). "COL4A6 may promote tumor aggressiveness and chemoresistance via the E2F/DDR1 axis, and COL4A6 expression can predict clinical outcomes in patients with ovarian cancer." (PMID 40603853, 2025).
familial hemorrhagic nephritis (2 papers, 2020 to 2021). "The absence of COL4A6 may cause familial hemorrhagic nephritis." (PMID 33490103, 2020).
adenoma (1 paper, 2013). A neoplasm arising from the epithelium. "CDH20 and LAMA3 were mutated in the adenoma while NRXN3 and COL4A6 were mutated in the adenocarcinoma from the same patient, suggesting for the first time that genetic alterations in the cell adhesion pathway occur as early as in the adenoma." (PMID 23301059, 2013). "We found that CDH20 and LAMA3 were mutated in the adenoma while NRXN3 and COL4A6 were mutated in the adenocarcinoma." (PMID 23301059, 2013).
autism (1 paper, 2024). Persistent deficits in social interaction and communication and interaction as well as a markedly restricted repertoire of activity and interest as well as repetitive patterns of behavior. "Studies have shown that NCAM2 is associated with autism and Down’s syndrome, whereas COL4A6 methylation is linked to high genetic risk of development of mood disorders." (PMID 38638145, 2024).
cervical cancer (1 paper, 2023). A primary or metastatic malignant neoplasm involving the cervix. "In this study, COL4A6 was found to be under-expressed in cervical cancer tissues and is a high-risk prognostic marker." (PMID 37042849, 2023).
Cirrhosis (1 paper, 2015). A chronic disorder of the liver in which liver tissue becomes scarred and is partially replaced by regenerative nodules and fibrotic tissue resulting in loss of liver function. "Patients with cirrhosis showed increased expression in blood of eight genes coding for collagen synthesis COL4A6, COL5A1, COL11A2, COL12A1, COL27A1, COL28A1, COL23A1, COL14A1." (PMID 26317806, 2015).
colon adenoma (1 paper, 2013). An adenoma that arises from the colon. "Among these mutated genes, mutations in APC, FBXW7, KIAA1409, COL4A6, FAM181A, TFR2 and NRXN3 were previously reported in colon adenomas or adenocarcinomas." (PMID 23301059, 2013).
diabetes (1 paper, 2024). "In addition to the increased expression of the ECM protein COL4A6, LAMB2, and HIC5 (encoded by Tgfb1i1) are also present in the livers of mice with late-stage diabetes and HFD/STZ." (PMID 39494341, 2024).
esophageal squamous cell carcinoma (1 paper, 2016). Esophageal squamous cell carcinoma (ESCC) is a type of esophageal carcinoma (EC) that can affect any part of the esophagus, but is usually located in the upper or middle third. "COL4A6 encodes the alpha-6 chain of type IV collagen of basal membranes and is related to the prognosis of esophageal squamous cell carcinoma." (PMID 27855662, 2016).
glioma (1 paper, 2025). A benign or malignant brain and spinal cord tumor that arises from glial cells (astrocytes, oligodendrocytes, ependymal cells). "In TCGA, GEO (GSE50161, GES7696, GES4290) and CGGA (mRNAseq_325) databases, we found the COL4A1, COL4A2 and COL4A6 expression were significantly increased in glioma tissues." (PMID 40351420, 2025). "By using Oncomine databases, we found that the expression of COL4A1 to COL4A6 was closely related to brain and CNS cancer." (PMID 40351420, 2025).
metastatic colorectal cancer (1 paper, 2025). "DDR1 expression is associated with decreased OS in patients with metastatic colorectal cancer, and DDR1 phosphorylation is strongly increased in the corresponding metastatic lesions, indicating that COL4A6 promotes cell invasion via the E2F1/DDR1/FAK axis." (PMID 40603853, 2025).
non-syndromic hearing loss (1 paper, 2021). "To date, five X-linked genes have been found to be related to the etiology of non-syndromic hearing loss (NSHL): PRPS1 (DFNX1, OMIM:311850), POU3F4 (DFNX2, OMIM:300039), SMPX (DFNX4, OMIM:300226), AIFM1 (DFNX5, OMIM:300169) and COL4A6 (DFNX6, OMIM:303631)." (PMID 33860785, 2021).
oral cancer (1 paper, 2025). "This study identified differential expression of COL4A6 between human oral cancer and rats, potentially attributable to species specificity, differences in the tumor microenvironment, and distinct gene regulatory mechanisms." (PMID 41415031, 2025). "Notably, COL4A6 exhibited an upward trend in expression within human oral cancer tissues, starkly contrasting with the downregulation observed in rat models." (PMID 41415031, 2025).
osteoporosis (1 paper, 2025). A condition of reduced bone mass, with decreased cortical thickness and a decrease in the number and size of the trabeculae of cancellous bone (but normal chemical composition), resulting in increased fracture incidence. "This study employed network pharmacology and bioinformatics analysis to identify two biomarkers (COL4A6 and NKX3-1) closely associated with the ISR pathway during JWSTZYD treatment for osteoporosis." (PMID 41195206, 2025).
pancreatic cancer (1 paper, 2025). "While Type IV collagen has been linked to the tumor stroma in pancreatic cancer, COL4A6’s specific role in OC progression, particularly in advanced stages, remains poorly understood." (PMID 40603853, 2025). "Given its stromal localization, targeting COL4A6 with antibody-drug conjugates (ADCs) or other therapeutic strategies may offer a novel approach to overcoming chemoresistance, as has been explored in pancreatic cancer." (PMID 40603853, 2025).
Parkinson disease (1 paper, 2025). A progressive degenerative disorder of the central nervous system characterized by loss of dopamine producing neurons in the substantia nigra and the presence of Lewy bodies in the substantia nigra and locus coeruleus. "COL4A6 was significantly associated with spliceosome, proteasome, and Parkinson’s disease pathways, while NKX3–1 was enriched in spliceosome, olfactory transduction, and cell cycle pathways." (PMID 41195206, 2025).
prostate tumor (1 paper, 2023). "SPP1 and CLDN8 were upregulated in prostate tumor tissues, whereas COL4A6, RND3, DPT, EFS, and TGFB1I1 were downregulated." (PMID 37251946, 2023). "CRISP3 was upregulated; conversely, OGN, SPOCK3, COL4A6, CCBE1, and FLRT3 were downregulated in prostate tumor tissues." (PMID 37251946, 2023).
Tay-Sachs disease (1 paper, 2026). GM2 gangliosidosis, variant B or Tay-Sachs disease is marked by accumulation of G2 gangliosides due to hexosaminidase A deficiency. "The first family presented a missense COL4A6 variant (NM_033641.4: c.1480G>A p.(Gly494Arg)), accounting for hearing loss, while a likely pathogenic HEXA variant (NM_000520.6: c.902T>G p.(Met301Arg)) explained Tay-Sachs disease features." (PMID 41092388, 2026).
tongue cancer (1 paper, 2020). A malignant neoplasm affecting the tongue. "Sequencing and qPCR results demonstrated that COL4A1 and COL4A6 were significantly upregulated in tongue cancer, suggesting that these genes may play important roles in the occurrence and development of tongue cancer." (PMID 32236620, 2020).